VBP1 (VHL binding protein 1)
Description:
Binds specifically to cytosolic chaperonin (c-CPN) and transfers target proteins to it. Binds to nascent polypeptide chain and promotes folding in an environment in which there are many competing pathways for nonnative proteins.
Synonyms: VBP-1; PFDN3; PFD3; HIBBJ46
Tractability: Small molecule: a structure with a bound ligand is known. PROTAC: ubiquitination databases record sites on it; its protein half-life has been measured.
Gene: Protein-coding gene on chromosome X (155,197,007 to 155,239,841, forward strand). Ensembl gene ENSG00000155959.
Subcellular location: Cytoplasm; Nucleus
Subcellular location (Human Protein Atlas): Cytosol; Vesicles
Pathways (Reactome):
Metabolism of proteins: Prefoldin mediated transfer of substrate to CCT/TriC
Gene Ontology:
Molecular function: amyloid-beta binding; protein binding; tubulin binding
Biological process: negative regulation of amyloid fibril formation; protein folding; protein stabilization; tubulin complex assembly
Cellular component: cytosol; prefoldin complex; cytoplasm; protein folding chaperone complex; nucleus
Homologues: Orthologues: chimpanzee VBP1 (100% identical), macaque VBP1 (99% identical), mouse Vbp1 (97% identical), dog VBP1 (96% identical), guinea pig VBP1 (96% identical), pig VBP1 (96% identical), zebrafish vbp1 (77% identical), Drosophila melanogaster mgr (50% identical), Caenorhabditis elegans pfd-3 (38% identical), Drosophila melanogaster CG15676 (25% identical).
Diseases named in the same sentence as VBP1 in open-access papers:
VBP1 is named in the same sentence as 17 diseases in open-access papers, as found by Europe PMC text mining. Sharing a sentence is not in itself a finding about the gene and the disease. The quoted sentences say what the papers report.
clear cell renal carcinoma (2 papers, 2020 to 2023). A malignant epithelial neoplasm of the kidney characterized by the presence of lipid-containing clear cells within a vascular network. "In patients with clear cell renal cell carcinoma (ccRCC), lower VBP1 expression was associated with worse survival outcomes." (PMID 37201586, 2023). "We, therefore, overexpressed or knocked down VBP1 protein in VHL-deficient clear-cell renal carcinoma 786-O cells." (PMID 32989053, 2020).
colorectal cancer (2 papers, 2020 to 2023). A primary or metastatic malignant neoplasm that affects the colon or rectum. "It is interesting to know whether alternation of VBP1 decreases the proliferation of colorectal cancers." (PMID 32989053, 2020). "Because colorectal cancers often display overactivated Wnt/β-catenin signaling and VBP1 regulates the protein stability of TCF/LEFs in HCT116 colon cancer cells, we next determined whether VBP1 has a physiological role in colorectal cancer cells." (PMID 32989053, 2020). "However, our findings contrast with those of Kim's study, which reported no physical interaction between VBP1 and HIF-1α in human colorectal carcinoma HCT116 cells." (PMID 37201586, 2023).
glioblastoma (2 papers, 2014). The most malignant astrocytic tumor (WHO grade IV). "Proteomic studies of glioblastoma cells treated with carnosine showed significantly reduced expression of VBP1 protein and mRNA." (PMID 24886661, 2014). "Proteomic studies of glioblastoma cells after treatment with carnosine revealed significantly reduced expression of von Hippel-Lindau binding protein 1 (VBP1), a protein that binds to the von Hippel-Lindau protein and thus is linked to HIF-1α signaling." (PMID 24886661, 2014).
renal cell carcinoma (2 papers, 2017 to 2024). "VBP1 plays a role in the transport of the Von Hippel-Lindau protein from the perinuclear granules to the nucleus or cytoplasm, the mutation and loss of VBP1 may be related to the renal-cell carcinoma development." (PMID 29026100, 2017). "While VBP1's involvement in colon and renal cell carcinoma progression is documented, its role in ESCC is less explored." (PMID 38700744, 2024).
colon cancer (1 paper, 2020). "Knockdown of VBP1 also decreased TCF7L1 and TCF7L2 protein levels in Wnt-activated HCT116 colon cancer cells, which harbor an oncogenic mutation in β-catenin." (PMID 32989053, 2020). "Because the HEK293T cell line was regarded as a Wnt-off cell line, we want to determine whether knockdown of VBP1 regulates TCF/LEF protein stability in Wnt-activated colon cancer cells." (PMID 32989053, 2020). "Similarly, knockdown of VBP1 in Wnt-activated HCT116 colon cancer cells also increased the interaction between TCF7L2 and pVHL." (PMID 32989053, 2020).
liver cancer (1 paper, 2022). An epithelial or non-epithelial malignant neoplasm that arises from the liver. "Higher expression of PFDN1 (HR = 1.49, 95% CI: 1.05–2.10, p = 0.025), PFDN2 (HR = 1.49, 95% CI: 1.05–2.11, p = 0.024), VBP1 (HR = 1.47, 95% CI: 1.03–2.08, p = 0.031), and PFDN4 (HR = 1.78, 95% CI: 1.25–2.53, p = 0.001) was significantly associated with shorter OS of liver cancer patients." (PMID 36438659, 2022).
melanoma (1 paper, 2024). A malignant, usually aggressive tumor composed of atypical, neoplastic melanocytes. "In conclusion, we identified NLGN4X and its target VBP1 as novel melanoma markers down-regulated during melanoma progression." (PMID 38902533, 2024). "To further evaluate the role of NLGN4X and VBP1 in melanoma patients, we used mRNA microarray data from the TCGA consortium." (PMID 38902533, 2024). "In line, loss of VBP1, a member of the prefoldin complex, has been shown to trigger HIF1A accumulation in B16F10 mouse melanoma cells and in zebrafish." (PMID 38902533, 2024). "Moreover, loss of VBP1 was sufficient for accumulation of HIF1A and HIF1A signalling was further shown to be essential for the acquisition of migratory properties in melanoma." (PMID 38902533, 2024). "Furthermore, we showed that loss of NLGN4X reduced the neuronal gene signature in melanoma cells and triggered HIF signalling by VBP1 suppression." (PMID 38902533, 2024). "Hence, we targeted VBP1 in both melanoma cell lines by siRNA." (PMID 38902533, 2024). "To validate this finding, we acquired an additional 80 clinical melanoma patient samples from an Austrian cohort, which we subjected to immunohistochemical staining for NLGN4X and VBP1." (PMID 38902533, 2024). "To analyse the correlation between NLGN4X and VBP1 in our melanoma samples, we performed Pearson correlation analysis and identified NLGN4X to significantly correlate with VBP1 (R = 0.581, P < 0.001)." (PMID 38902533, 2024).
ovarian carcinoma (1 paper, 2021). A malignant neoplasm originating from the surface ovarian epithelium. "On the other hand, our study for the first time showed that interaction of HDAC and chaperone system including chaperone HSP70, chaperonin TCP-1α and co-chaperone VHL-binding protein-1 (VBP-1) maintains the stringent quality control of pVHL in ovarian cancer." (PMID 34329303, 2021).
renal carcinoma (1 paper, 2023). A carcinoma arising from the epithelium of the renal parenchyma or the renal pelvis. "To test this hypothesis, we investigated whether VBP1 regulated HIF-1α in the pVHL-deficient RCC4 renal carcinoma cells, which demonstrate high endogenous levels of HIF-1α and HIF-2α proteins." (PMID 37201586, 2023). "To further determine whether VBP1 modulates endogenous HIF-2α protein levels, we used pVHL-deficient renal carcinoma (786-O) cells which have high endogenous levels of HIF-2α protein." (PMID 37201586, 2023).
uveal melanoma (1 paper, 2003). A melanoma derived from melanocytes of the uveal tract. "ET2, LAMR1, VBP1 and CUL2 belong to the group of genes exhibiting the most discriminating differential expression ratio in uveal melanomas cell lines compared to the expression ratio of the normal melanocytes." (PMID 14612903, 2003). "An important role in uveal melanoma development is now suggested for Laminin Receptor 1 (LAMR1), Endothelin 2 (ET2), Von Hippel Lindau Binding Protein 1 (VBP1) and Cullin 2 (CUL2) genes, since their expression levels discriminate between two classes of uveal melanoma." (PMID 14612903, 2003).
tumor (5 papers, 2003 to 2024). "Our findings indicated that the tumor growth rate and weight were notably higher in the VBP1-OE group than the NC group." (PMID 38700744, 2024). "Functional experiments confirmed that VBP1 significantly accelerated tumor proliferation both in vitro and in vivo." (PMID 38700744, 2024). "VBP1 is identified as a pivotal gene within the hypoxia-related prognostic signature, and it significantly promotes tumor proliferation in ESCC." (PMID 38700744, 2024). "Within this hypoxia-related gene model, VBP1 emerged as a pivotal gene that promotes tumor proliferation in ESCC." (PMID 38700744, 2024). "Recent studies have reported that VBP1 performs tumor suppressor functions through multiple mechanisms such as HIF-1α degradation in a pVHL-dependent manner and as a co-chaperone in the correct folding of newly synthesized pVHL." (PMID 37201586, 2023). "In our context, VBP1 inhibition could halt tumor growth, signposting a potential therapeutic target." (PMID 38700744, 2024). "Furthermore, immunohistochemical analysis of tumor tissues confirmed the elevated expression of VBP1 and Ki-67 in the VBP1 OE group." (PMID 38700744, 2024). "J. K. Ahn reported that VBP1 elevates pVHL-induced HIF-1α ubiquitination, destabilizing HIF-1α and potentially inhibiting tumor metastasis." (PMID 38700744, 2024). "VBP1 is correlated with poor ESCC outcomes and is seen to foster tumor progression both in vitro and in vivo." (PMID 38700744, 2024). "Depletion of VBP1 was sufficient for activation of the oncogenic HIF1A pathway, which drives tumour cell migration." (PMID 38902533, 2024). "PFDN3, also known as von Hippel-Lindau (VHL) binding protein 1 (VBP1), regulates the tubulin stability by cooperating with VHL, a tumor suppressor, in Drosophila." (PMID 31957800, 2020). "Pearson test identified one significant correlation between gene expression and histopathological parameters of the tumours; ET2, LAMR1 and VBP1 were positively correlated with PAS-positive loops (P=0.005, 0.028 and 0.01, respectively)." (PMID 14612903, 2003). "Furthermore, we identified NLGN4X and VBP1 to play fundamental roles in HIF transcription factor stabilisation and tumour cell migration." (PMID 38902533, 2024). "The expression patterns of the genes VBP1 and CUL2 exhibited a small overlap in both assays and revealed no elevated expression levels in the primary tumour samples." (PMID 14612903, 2003).
cancer (2 papers, 2022 to 2023). A tumor composed of atypical neoplastic, often pleomorphic cells that invade other tissues. "A better understanding of the roles of VBP1 in CHIP-mediated HIF-1α stability may provide further insights into their roles in human diseases including cancers and contribute to the development of drugs targeting HIF-1α signaling." (PMID 37201586, 2023). "PFDN3, also known as von Hippel–Lindau (VHL)-binding protein 1 (VBP1), represses cancer metastasis by enhancing HIF-1α degradation induced by pVHL." (PMID 36438659, 2022). "PFDN3, also known as VBP1, might play opposite roles in different cancers." (PMID 36438659, 2022).
VBP1 also shares sentences with these, for which no sentence is quoted: gastric cancer (2 papers); non-small cell lung carcinoma (2); esophageal squamous cell carcinoma (1); infection (1); viral infection (1).